NLRP3 (NLR family pyrin domain containing 3)
Diseases named in the same sentence as NLRP3 in open-access papers (continued):
Sharing a sentence is not in itself a finding about the gene and the disease.
Arterial thrombosis (2 papers, 2022 to 2023). The formation of a blood clot inside an artery. "A remarkable reduction in αIIbβ3 signaling transduction was observed together with the the release of IL-1β in NLRP3 deficient platelets, suggesting NLRP3 inflammasome contribute to the hemostasis and arterial thrombosis with the mediation of IL-1β release and αIIbβ3 signaling." (PMID 36204568, 2022).
B-cell lymphoma (2 papers, 2021 to 2024). "Research also highlighted the role of the NLRP3 inflammasome in other less frequent B-cell NHLs." (PMID 38397043, 2024). "Interestingly, for some B-cell NHL subtypes, NLRP3 inflammasome activation was reported to act as a negative regulator of lymphomagenesis." (PMID 38397043, 2024).
bacterial meningitis (2 papers, 2021). Inflammation of the membranes surrounding the brain and spinal cord due to a bacterial infection. "However, NLRP3 levels in the CSF from patients with bacterial meningitis have not been determined." (PMID 35145923, 2021).
biliary atresia (2 papers, 2020 to 2021). A rare, biliary tract disease characterized by progressive obliterative cholangiopathy of the intra- and extrahepatic bile ducts, occurring in the embryonic/ perinatal period, leading to severe and persistent neonatal jaundice and acholic stool. "In biliary atresia, a neonatal obstructive cholangiopathy, increased expression of NLRP3, Caspase-1 and IL-1R1 has been demonstrated in the livers of patients at the time of diagnosis." (PMID 32192118, 2020). "Besides, NLRP3 inflammasome became an object of interest, as its activity is upregulated in cholestatic liver injury in PSC, PBC, and biliary atresia." (PMID 34685598, 2021).
Brain Tumor (2 papers, 2016 to 2023). "However, the potential mechanism of NLRP3 inflammasome in the progress of brain tumor has not been totally understood." (PMID 27652274, 2016).
bronchitis (2 papers, 2022 to 2025). An acute or chronic inflammatory process affecting the bronchi. "Uric acid could trigger ROS production and stimulated the release of NLRP3 inflammasome, which occurred following childhood wheezing or bronchitis and was related to IL-1β generation." (PMID 36059973, 2022).
brucellosis (2 papers, 2009 to 2022). Brucellosis is a bacterial infection that spreads from animals to people via unpasteurized dairy products or by exposure to contaminated animal products or infected animals. "Compared with healthy controls, chronic brucellosis patients present an increasing tendency of NLRP3, significantly decreased AIM2 expression, and significantly increased Caspase-1 expression, with no significant changes in ASC." (PMID 36068262, 2022). "The expression levels of AIM2, NLRP3, ASC, and Caspase-1 were investigated in patients with acute brucellosis and chronic brucellosis as well as healthy controls." (PMID 36068262, 2022). "This study aims to investigate the expression levels of AIM2, NLRP3, ASC, and Caspase-1 inflammasomes in acute and chronic brucellosis patients to reveal the possible mechanism of Brucella immune escape." (PMID 36068262, 2022). "Compared with healthy controls, patients with acute brucellosis show significantly higher AIM2 expression and significantly lower ACS expression, with no significant changes in NLRP3 but an increasing tendency of Caspase-1 genes." (PMID 36068262, 2022).
Burkitt lymphoma (2 papers, 2022 to 2024). A rare form of malignant mature B-cell non-Hodgkin lymphoma. "NLRP3 was also shown to exert an antitumorigenic effect in Burkitt lymphoma triggered by Epstein–Barr virus (EBV)." (PMID 38397043, 2024). "Interestingly, for CLL/SLL and Burkitt lymphoma, NLRP3 inflammasome activation acts as a tumor-suppressive factor, while for CTCLs, NLRP3 inflammasome activation was associated with both pro- and anti-tumorigenic effects." (PMID 38397043, 2024). "In Burkitt lymphoma triggered by EBV, the downregulated NLRP3 inflammasome could not prevent a latent infection favoring pathogenesis." (PMID 35897704, 2022).
Cachexia (2 papers, 2021 to 2022). Severe weight loss, wasting of muscle, loss of appetite, and general debility related to a chronic disease. "The NLRP3 inflammasome is known to become activated upon metabolic disturbances and boosts pro-inflammatory immune reactions via IL-1β, which not only drives myocardial remodeling but also is the hallmark of cachexia, metabolic de-regulation." (PMID 35967380, 2022). "As far as we know, this is the first study to show that the NLRP3 pathway is also activated in human cachexia (similarly to the previously demonstrated in rodents)." (PMID 34630405, 2021). "According to the data presented here, IL-6 could be here an important mediator between de-regulated metabolism in cachexia and inflammatory response in fibroblasts from the LV and SM regarding NLRP3 inflammasome activity." (PMID 35967380, 2022).
calcification (2 papers, 2020 to 2021). Process by which organic tissue becomes hardened by the physiologic deposit of calcium salts. "Findings answers to these questions will lead to the development of drugs targeting the NLRP3 inflammasome as a therapeutic approach to treat bone disease and vascular calcification." (PMID 33215255, 2021).
cerebral artery occlusion (2 papers, 2018 to 2026). "We therefore hypothesized that MCC950, a selective NLRP3-inflammasome inhibitor provides protection in mouse model of transient middle cerebral artery occlusion (tMCAO)." (PMID 29654318, 2018).
cerebral palsy (2 papers, 2021 to 2023). A group of disorders affecting the development of movement and posture, often accompanied by disturbances of sensation, perception, cognition, and behavior. "Therefore, the current study proves that Tuina may enhance the cognitive functions of cerebral palsy rats and further explore whether this effect is related to the inhibition of NLRP3-induced pyroptosis." (PMID 34691200, 2021).
cervical (2 papers, 2021 to 2023). "Accordingly, the rs10754558 G allele may alter the function of NLRP3, thereby influencing IL-1β and IL-18 secretion in a manner that enhances inflammatory cascade activity and drives pathological changes conducive to cervical oncogenesis." (PMID 37885032, 2023). "Then we designed a series of studies for the cytotoxic, anti-cervicitis, anti-inflammatory, and changes of inflammatory factors as well as NLRP3." (PMID 34684794, 2021). "Moreover, the active diterpenoids and the regulation of NLRP3 are important for finding new agents in treating cervicitis." (PMID 34684794, 2021).
childhood asthma (2 papers, 2021 to 2025). "Perhaps targeting NLRP3 during these early life events may provide a common therapeutic pathway for controlling long term sequelae that are often observed later in these children, including childhood asthma." (PMID 33923693, 2021).
Chlamydia infection (2 papers, 2011 to 2020). "Only a minor role for Syk has been reported in the case of IL-1beta production stimulated by Chlamydia infection, whereas Syk played a major role in NLRP3 activation during fungal or malarial infections." (PMID 21740493, 2011).
cholangitis (2 papers, 2020). An acute or chronic inflammatory process affecting the biliary tract. "In another study using the OVAbil mouse model of antigen-mediated cholangitis, NLRP3 loss unexpectedly led to a more severe cholangitis phenotype." (PMID 33353156, 2020). "recently described a central role of NLRP3 in driving IL-17 in an infectious model of cholangitis as well." (PMID 32716024, 2020). "In summary, our data suggest that activation of NLRP3 attenuates this antigen-mediated OVAbil model of cholangitis." (PMID 32716024, 2020). "Here, we addressed the role of NLRP3 in the OVAbil mouse model of antigen-mediated cholangitis." (PMID 32716024, 2020). "We observed a more severe histopathological phenotype of cholangitis in absence of NLRP3, characterized by loss of bile ducts and larger inflammatory foci and higher levels of IL- 6 and CXCL10 as compared with NLRP3 sufficient mice." (PMID 32716024, 2020).
cholesteatoma (2 papers, 2021 to 2022). A pathologic process characterized by the proliferation of keratinizing squamous epithelium resulting in the accumulation of keratin and cells in the middle ear and/or mastoid. "NLRP3 protein was observed in infiltrated inflammatory cells of COM with cholesteatoma patients and COM patients, in association with significantly increased NLRP3 mRNA levels." (PMID 35216465, 2022). "In one study, expression of NLRP3 in middle-ear samples was compared between cochlear implant surgery patients with COM with cholesteatoma and those with COM and normal middle-ear mucosa through reverse transcription polymerase chain reaction (RT-PCR) analysis and immunohistochemical studies." (PMID 35216465, 2022).
chronic gastritis (2 papers, 2024 to 2025). Inflammation of the stomach that is chronic in nature. "CAG mice infected with Helicobacter were given Chaenomeles speciosa total triterpenoids, and their chronic gastritis and atrophy glands were improved by the reduction of thioredoxin-interacting protein (TXNIP), NLRP3, pro-caspase-1, and caspase-1 levels." (PMID 40264171, 2025).
chronic meningitis (2 papers, 2010 to 2022). Chronic form of meningitis (disease). "Fever and rash were the most prevalent clinical presentations while chronic meningitis and neurosensory hearing loss were frequently seen in NLRP3-AID patients." (PMID 35668534, 2022).
clear cell renal cell carcinoma (2 papers, 2020 to 2025). "In their study, they have found high expression levels of NLRP3 pathway components in clear cell renal cell carcinoma patient samples as compared to the experiment's controls, thus suggesting a crucial role of NLRP3 inflammasome in this type of tumor." (PMID 33015196, 2020). "In a study on kidney clear cell carcinoma (KIRC), NLRP3 expression was significantly elevated in tumor tissues, and NLRP3 mRNA expression appeared to be regulated by promoter methylation." (PMID 40718836, 2025).
crescentic glomerulonephritis (2 papers, 2011 to 2016). A histopathologic term for a pattern of diseases characterized by extensive crescent formation in the glomeruli; patients present clinically with rapid deterioration of renal function, and possible progression to end-stage renal failure within weeks or months. "Although inhibition of PI3k/Akt and MAPK signaling pathways by EGCG has been reported involved in the anti-inflammatory mechanism in ameliorating crescentic glomerulonephritis, the NLRs, which are cystolic PRRs, and NLR-activated inflammasome, typically NLRP3, aroused our interest." (PMID 26866373, 2016). "We therefore conclude that GBM antiserum induces crescentic glomerulonephritis independent of the NLRP3 inflammasome and of ASC-mediated activation of caspase-1." (PMID 22046355, 2011).
Crohn's colitis (2 papers, 2022 to 2023). Crohn's disease affecting the colon. "Our outcomes revealed that inhibiting pyroptosis caused by NLRP3 inflammasome was an important mechanism by which circPRKAR1B knockdown alleviated Crohn's colitis via targeting autophagy." (PMID 37679886, 2023). "Our study reveals that circPRKAR1B upregulation, which is at least partially induced by METTL3‐mediated m6A modification, promotes Crohn's colitis by aggravating NLRP3 inflammasome‐mediated pyroptosis via autophagy impairment." (PMID 37679886, 2023). "Our study reveals that METTL3‐mediated m6A modification of circPRKAR1B promotes Crohn's colitis by aggravating NLRP3 inflammasome‐mediated pyroptosis via autophagy impairment in colonic epithelial cells." (PMID 37679886, 2023). "In conclusion, this study suggests that circGMCL1 protects intestinal barrier function against Crohn’s colitis through alleviating NLRP3 inflammasome-mediated epithelial pyroptosis by promoting autophagy through regulating ANXA7 via sponging miR-124-3p." (PMID 36088391, 2022). "This study suggests that circGMCL1 protects intestinal barrier function against Crohn’s colitis through alleviating NLRP3 inflammasome-mediated epithelial pyroptosis by promoting autophagy through regulating ANXA7 via sponging miR-124-3p." (PMID 36088391, 2022).
cryptococcal infection (2 papers, 2017 to 2020). "Notably, mice lacking NLRP3 or ASC are more susceptible to cryptococcal infection with encapsulated yeast cells, whereas infection with acapsular yeast cells results in higher fungal burdens in the lungs in NLRP3 knockout mice." (PMID 33380899, 2020).
Cutaneous T Cell Lymphoma (2 papers, 2021 to 2025). "A further layer of complexity is added by the positive feedback between NLRP3 and the IL-4 promoter, particularly in malignant CD4+ T cells of cutaneous T cell lymphoma, which perpetuates high IL-4 production and reinforces the Th2-dominant, immunosuppressive environment." (PMID 40864740, 2025).
cystinosis (2 papers, 2022 to 2025). Cystinosis is a metabolic disease characterized by an accumulation of cystine inside the lysosomes, causing damage in different organs and tissues, particularly in the kidneys and eyes. "The relevance to cystinosis stems from the fact that several of these NLRP3-activating stimuli are present in cystinotic cells." (PMID 40943162, 2025). "Thus, despite the current absence of direct experimental evidence in corneal tissue from cystinosis patients, the convergence of these molecular features strongly supports a testable hypothesis: NLRP3 inflammasome activation is a plausible driver of corneal inflammation in cystinosis." (PMID 40943162, 2025).
Diarrhea (2 papers, 2020 to 2021). Abnormally increased frequency (usually defined as three or more) loose or watery bowel movements a day. "In the present study, L. rhamnosus supplementation decreased the gene expression of NLRP3 and HSP70, increased AQP expression, which may be one of the primary mechanisms to alleviate intestinal mucosal injury and diarrhoea caused by ETEC." (PMID 34796123, 2021).
dissection (2 papers, 2021 to 2022). The separation and isolation of tissues for surgical purposes, or for the analysis or study of their structures. "Our in vivo study demonstrated that inhibition of ceramide de novo synthesis by myriocin significantly alleviated BAPN-induced aortic dissection, and NLRP3 mRNA and protein levels were both decreased in BAPN-treated mouse aortae." (PMID 35211530, 2022). "Both smooth muscle actin degradation and the incidence of aortic dissections was reduced in Nlrp3 and caspase-1 knockout mice, as well as by treatment with glyburide, which is an antidiabetic drug incidentally inhibiting Nlrp3–caspase-1 inflammasome complex formation." (PMID 34572082, 2021). "Regarding aortic dissection in the BAPN model, activation of PKM2 suppresses Nlrp3 mediated Il-1β secretion and, in this way, both reduced lethality due to aortic rupture as well as the maximal aortic diameter." (PMID 34572082, 2021).
disseminated candidiasis (2 papers, 2011 to 2021). Systemic candidiasis occurs when Candida yeast enters the bloodstream and may spread (becoming disseminated candidiasis) to other organs, including the central nervous system, kidneys, liver, bones, muscles, joints, spleen, or eyes. "This indicates that caspase-1 and ASC have strongly protective antifungal capacities through controlling Th1 and Th17 responses during disseminated candidiasis, due to activation of the NLRP3/ASC/caspase-1 pyroptosis pathway." (PMID 34908455, 2021). "Candida induced activation of the NLRP3/ASC inflammasome then provides a critical amplification of the innate response leading to protection of the host from overwhelming mucosal and disseminated candidiasis." (PMID 22174673, 2011).
duodenogastric reflux (2 papers, 2024 to 2025). Retrograde flow of duodenal contents (bile acids; pancreatic juice) into the stomach. "Another negative regulator is the farnesoid X receptor (FXR), which inhibits the duodenogastric reflux-induced NLRP3 inflammasome and pyroptosis by physically interacting with NLRP3 and caspase-1." (PMID 40307577, 2025).
dysferlinopathy (2 papers, 2014 to 2025). "Supporting the relevance of inflammasome activation in dysferlinopathy, previous studies have shown increased levels of NLRP3, ASC, active caspase-1, and mature IL-1β in skeletal muscles from dysferlin-deficient (A/J) mice." (PMID 41155239, 2025). "To date, encouraging results were obtained by studying the NLRP3 inflammasome signalling pathway so that it is now considered as a good therapeutic target for dysferlinopathy." (PMID 24959590, 2014).
endometrial tumor (2 papers, 2020 to 2025). "In the mouse model, H2 exposure significantly inhibited endometrial tumor growth compared to controls (p < 0.01) and increased expression of NLRP3, caspase-1, and GSDMD, confirming the promotion of pyroptosis." (PMID 41140697, 2025).
epilepsy syndrome (2 papers, 2024). A syndrome that has a characteristic cluster of clinical features and/or lectroencephalographic (EEG) findings that reflect underlying epileptic activity. "Curcumin has been reported to inhibit IL-1β release and prevent inflammation via the inhibition of NLRP3 and suppressed KA-induced epileptic syndrome via inhibiting NLRP3 inflammasome activation in Sprague Dawley rats." (PMID 38892264, 2024).
Epiphyseal dysplasia (2 papers, 2017 to 2022). "In this study, we find that activation of NLRP3 in myeloid cells, but not mesenchymal cells triggers chronic inflammation, which ultimately, causes growth plate and epiphyseal dysplasia in mice." (PMID 28687790, 2017).
esophageal cancer (2 papers, 2025 to 2026). A primary or metastatic malignant neoplasm involving the esophagus. "Our results indicate that Ori can reduce Bcl-2 mRNA levels and increase Bax mRNA levels in esophageal tissue of mice with esophageal cancer, suggesting that Ori can promote tumor cell apoptosis by inhibiting NLRP3 inflammasome activation." (PMID 40606986, 2025). "This study provides evidence indicating that Ori may inhibit inflammatory response by inhibiting TLR4/NF-κB/NLRP3 inflammasome activation, ultimately exert anti esophageal cancer effects." (PMID 40606986, 2025). "Explore whether Oridonin (Ori) improves esophageal cancer by interfering in the TLR4/NF-κB/NLRP3 inflammasome." (PMID 40606986, 2025). "For example, this study only conducted pharmacological experiments and did not conduct in vivo knockdown or overexpression bidirectional validation of the intervention effect of Ori on TLR4/NF-κB/NLRP3 in esophageal cancer mice, as well as its downstream effects." (PMID 40606986, 2025).
eye inflammation (2 papers, 2022 to 2023). "Due to their huge therapeutic potential, MSCs and MSC-Exos have been used in several clinical trials to attenuate ongoing NLRP3-driven eye inflammation." (PMID 37759549, 2023).
familial atypical cold urticaria (2 papers, 2024 to 2025). "Mutations in the PLCG2 and NLRP3 genes cause familial cold autoinflammatory syndrome 3 and 1, respectively." (PMID 38177227, 2024).